SPP1 (secreted phosphoprotein 1)
Diseases named in the same sentence as SPP1 in open-access papers (continued):
Sharing a sentence is not in itself a finding about the gene and the disease.
urolithiasis (25 papers, 2013 to 2025). Stone(s) within the urinary tract. "Nonetheless, a recent study from South Asia found a significant association of the SPP1 rs2853744:G>T polymorphism with urolithiasis." (PMID 35385482, 2022). "Further, a comprehensive meta-analysis following a systematic literature search was also done to ascertain an evidence based account of any existent association regarding SPP1 promoter polymorphisms and risk of developing urolithiasis." (PMID 32842990, 2020). "All studies showed least one of the analyzed SPP1 genetic variants to be positively associated with the susceptibility of urolithiasis." (PMID 32842990, 2020). "We also observed a 1.68-fold positive association of a tri-allelic haplotype of these SPP1 promoter polymorphisms (G-C-dG) with risk of urolithiasis (OR = 1.68; p = 0.0079)." (PMID 32842990, 2020). "The results of present meta-analysis reveal that GG genotype of SPP1 rs2853744:G > T significantly increased the risk of urolithiasis by 1.37 fold in a recessive model." (PMID 32842990, 2020). "While, SPP1 rs11730582:T > C and rs11439060:delG>G polymorphisms were significantly associated with the risk of urolithiasis (OR = 1.78; p = 0.006 and OR = 1.60; p = 0.012, respectively) considering a recessive genetic model." (PMID 32842990, 2020). "In conclusion, we report significant association of 3 SPP1 polymorphisms with urolithiasis for the first time from South Asia, however, this association persisted only for SPP1 rs2853744:G > T polymorphism after meta-analysis of pooled studies." (PMID 32842990, 2020). "Considerable heterogeneity in correlation of these SPP1 polymorphisms and risk of urolithiasis have been reported by studies conducted in different ethnic groups." (PMID 32842990, 2020). "Among these, three studies also analyzed the association of other polymorphisms in SPP1 gene with urolithiasis." (PMID 32842990, 2020). "Three SPP1 promoter polymorphisms, rs2853744:G > T, rs11730582:T > C and rs11439060:delG>G, were found to be significantly associated with risk of urolithiasis in indigenous genetic association study (OR = 3.14; p = 0.006, OR = 1.78; p = 0.006 and OR = 1.60; p = 0.012, respectively)." (PMID 32842990, 2020). "In conclusion, the current study provides first account of a modest but statistically significant association of three SPP1 promoter polymorphisms and their tri-allelic haplotype with increased risk of urolithiasis from South-Asian region under the indicated genetic model." (PMID 32842990, 2020). "A total of 235 urolithiasis patients and 243 healthy controls, all of Pakistani ancestry, underwent genotyping for six SPP1 genetic polymorphisms in an effort to investigate potential association with urolithiasis using indigenous candidate gene association study design." (PMID 32842990, 2020). "We also demonstrated that subjects simultaneously harboring G-C-dG alleles of SPP1 rs2853744-rs11730582-rs11439060 polymorphisms, respectively, have 1.68 times increased risk of urolithiasis that is statistically significant as determined by haplotype association analysis." (PMID 32842990, 2020). "Frequency of G-C-dG haplotype (SPP1 rs2853744-rs11730582-rs11439060 polymorphisms, respectively) was significantly higher in urolithiasis patients as compared to controls (OR = 1.68; p = 0.0079), suggesting an association with increased risk of urolithiasis in haplotype analysis." (PMID 32842990, 2020). "Additionally, SPP1 rs2853744:G > T polymorphism showed significant associated with increased risk of urolithiasis in a dominant model (OR = 3.14; p = 0.006)." (PMID 32842990, 2020). "Therefore, in addition to presenting results of indigenous study, we also conducted a meta-analysis to clarify the possible association between SPP1 polymorphisms and risk of urolithiasis." (PMID 32842990, 2020). "In addition, evidence from meta-analysis part of the study supports the positive association of rs2853744:G > T SPP1 SNP and susceptibility of urolithiasis." (PMID 32842990, 2020).
urolithiasis (continued). "Further studies using larger sample sizes and analyses of gene-gene and gene-environment factors in diverse populations are suggested to validate and determine usefulness and broader relevance of SPP1 and other genetic polymorphisms in accessing risk and prognosis of urolithiasis." (PMID 32842990, 2020). "We also analyzed whether additional risk factors, including gender, early age at presentation, severe disease (multiple renal stones, recurrences), presence of familial history of urolithiasis and parental consanguinity modulated the SPP1 polymorphisms based potential genetic risk of urolithiasis." (PMID 32842990, 2020). "The SPP1 polymorphisms data was also analyzed considering sub-groups of Pakistani urolithiasis patients based on demographics (gender, age at first presentation), clinical features (stone multiplicity and stone recurrence) and histories (parental consanguinity and family history of urolithiasis)." (PMID 32842990, 2020). "With respect to genetic modulators, variations in allele/genotype distributions and LD pattern of SPP1 polymorphisms in different populations, reflecting a population specific genetic architecture, may determine substantial heterogeneity observed in genetic risk of urolithiasis." (PMID 32842990, 2020). "A number of genetic markers in different urolithiasis genes including SPP1, VDR, CaSR, urokinase, prothrombin, interleukins and others have been investigated in this regard." (PMID 32842990, 2020). "The overall results from meta-analysis, which included 4 studies, suggested a significant association of SPP1 rs2853744:G > T polymorphism with susceptibility of urolithiasis (OR = 1.37; p = 0.004), but not for other SPP1 polymorphic variants analyzed." (PMID 32842990, 2020). "However, results of previous studies regarding SPP1 polymorphisms and susceptibility to urolithiasis have apparent inconsistencies with no data available for local population." (PMID 32842990, 2020). "The observed overall heterogeneity in the results of different studies regarding association of SPP1 polymorphisms with urolithiasis may be attributable to many factors of genetic and non-genetic (including demographic, environmental and analytical variants) in origin." (PMID 32842990, 2020). "Except for SPP1, all validated DEPs have not been reported in the field of urolithiasis." (PMID 39452123, 2024).
Parkinson disease (24 papers, 2013 to 2025). A progressive degenerative disorder of the central nervous system characterized by loss of dopamine producing neurons in the substantia nigra and the presence of Lewy bodies in the substantia nigra and locus coeruleus. "In addition, elevated levels of SPP1 in cerebrospinal fluid of subjects with Parkinson’s disease were associated with more severe motor symptoms." (PMID 35347083, 2022).
viral infection (24 papers, 2014 to 2026). "In the primate models of HIV infection, viral infection causes a significant increase of SPP1 expression in the brain and cerebrospinal fluid." (PMID 32575635, 2020). "Western blot analysis of cytoplasmic fraction and nuclear fraction showed that more IRF3 was translocated into nucleus in macrophages from WT mice compared to that from OPN-deficient (Spp1−/−) mice after virus infection." (PMID 27026194, 2016). "Expression of these genes is associated with movement (MMP9, SPP1, ALCAM, and others), viral infection (APOC1, LGALS3, CD63, and others), and recruitment of phagocytes (APOE, CHI3L1, LGALS3, and others)." (PMID 32723919, 2020). "In conclusion, using proteomic analysis we found that the DEPs SPP1, IFIT5, ISG15, VCL, and SDC1 are significantly changed in PSV-infected PK-15 cells, suggesting that these proteins may be closely related to viral infection." (PMID 32575635, 2020).
bladder cancer (23 papers, 2011 to 2025). "Compared with normal bladder tissues, bladder cancer showed an increased expression level of SPP1 concomitantly associated with decreased promoter methylation of the SPP1 gene." (PMID 38067407, 2023). "The impact of the SPP1 gene mutations and/or amplifications on bladder cancer pathogenesis remains to be further verified." (PMID 38067407, 2023). "Herewith, we aimed to investigate the prognostic value of SPP1 expression and its association with other cancer-promoting factors in bladder cancer." (PMID 38067407, 2023). "We finally highlighted the association between SPP1 and immune infiltrating cells and immune checkpoint genes in bladder cancer." (PMID 38067407, 2023). "SPP1 might be clinically beneficial since its expression is significantly associated with the tumor grade, stage and survival of bladder cancer and other malignancies." (PMID 38067407, 2023). "Recent findings indicated that SPP1 possesses a broader role in bladder cancer (BC) pathogenesis than previously envisioned; however, the underlying mechanisms governing its expression, cellular localization, prognostic value and immune-related role in bladder cancer remain poorly understood." (PMID 38067407, 2023). "Spatial analysis revealed transcriptomic changes involving the immunomodulating gene SPP1 that has been also recently presented as a putative predictive biomarker for neoadjuvant chemotherapy in bladder cancer." (PMID 41388608, 2025). "The Kaplan–Meier survival curve showed that low SPP1 expression is an unfavorable prognostic indicator in bladder cancer patients (p = 0.02, log-rank)." (PMID 38067407, 2023). "In our bladder cancer cohort, high nuclear SPP1 expression was seen in only 8.0% of the patients and was significantly associated with a low tumor grade (p = 0.007)." (PMID 38067407, 2023). "The current study sheds light on the importance and the functional significance of SPP1 in bladder cancer." (PMID 38067407, 2023). "In the context of bladder cancer, the involvement of SPP1 in the pathogenesis of the disease is still poorly understood." (PMID 38067407, 2023). "In order to do so, tissue microarrays were constructed from 182 Saudi bladder cancer patients and immunohistochemistry staining was performed using an antibody against SPP1." (PMID 38067407, 2023). "Although immunosuppressive genes were expressed in M3 cluster macrophages, SPP1 (OPN) was the most differentially expressed gene in the group of HG bladder cancer-specific macrophages." (PMID 35265520, 2022). "The results revealed that bladder cancer cells secrete SPP1, which may interact with the integrin α4/β1 (ITGA4/ITGB1) complex of T cells to influence T cell function." (PMID 40665335, 2025). "Our study sheds light on the prognostic value of SPP1 expression in bladder cancer." (PMID 38067407, 2023). "Thus far, several potential biomarkers have been thoroughly studied and others are currently under investigation, such as SPP1 particularly in bladder cancer." (PMID 38067407, 2023). "Interaction between SPP1 and other proteins/genes and immune cell infiltrates may play an important role in the pathogenesis and could as a potential therapeutic target for bladder cancer." (PMID 38067407, 2023). "Our results suggested for the first time that high levels of SPP1 may play a role at an early stage of bladder cancer development (NMIBC)." (PMID 38067407, 2023). "The current investigation indicates that the SPP1 protein could serve as a prognostic biomarker and merit further investigation to validate its clinical usefulness in patients with bladder cancer." (PMID 38067407, 2023). "We next sought to investigate the mechanism by which SPP1 could promote tumor development in bladder cancer." (PMID 38067407, 2023). "In this regard, many studies have linked methylation of the CpG island sites of the promoter region to gene silencing and to alternative gene splicing in cancer which might be the case for the SPP1 gene in bladder cancer." (PMID 38067407, 2023).
bladder cancer (continued). "Future research is needed to evaluate the exact mechanism of how NRP2 and GLI2 communicate bidirectionally, how NRP2 modulates SPP1 transcription, and what implications this will have for development and progression of other cancer entities apart from bladder carcinoma." (PMID 32038994, 2019). "Thus far, the molecular mechanisms that underpin the link between SPP1 expression and bladder cancer progression and outcome remain largely unknown." (PMID 38067407, 2023). "Furthermore, non-muscle-invasive bladder cancer patients (NMIBC) showed a significant high expression of SPP1 (p = 0.019), supporting that increased expression of SPP1 could be an early event in bladder cancer development." (PMID 38067407, 2023). "The TCGA data indicated that SPP1 may play an important role in bladder cancer pathogenesis and prompted us to investigate the expression pattern and analyze the prognostic value of SPP1 in bladder cancer." (PMID 38067407, 2023). "Recent findings established the link between SPP1 and the epithelial-to-mesenchymal transition (EMT) through the NRP2 protein pathway in bladder cancer cell lines." (PMID 38067407, 2023). "No survival difference was observed for bladder cancer patients when nuclear SPP1 expression was taken in consideration." (PMID 38067407, 2023). "Additionally, SPP1 can also recognize albumin (ALB), integrin-A (ITGAV) and integrin-B (ITGB1) proteins whose expression was found to be highly increased at an early stage of bladder cancer development, using the TCGA-BLCA search engine." (PMID 38067407, 2023). "However, low cytoplasmic expression of SPP1 correlated with muscle-invasive bladder cancer patients and high cytoplasmic SPP1 expression was predominantly found in patients with non-muscle-invasive bladder cancer (NMIBC) which represents an early stage in bladder cancer development." (PMID 38067407, 2023).
Hyperglycemia (23 papers, 2011 to 2025). An increased concentration of glucose in the blood. "The increased H3K4me3 level in secreted phosphoprotein 1 (Spp1), the osteopontin gene, promoter were associated with Spp1 gene enhanced expression in hyperglycemia-treated human mesangial cells, whereas the levels of histone marks were linked to increases of Spp1 expression in animal studies." (PMID 36983082, 2023). "Spp1−/− and WT mice both developed comparable degrees of hyperglycaemia early after streptozotocin (STZ) treatment (plasma glucose 378 ± 16 mg/dL and 348 ± 20 mg/dL, respectively), indicating comparable efficiency of STZ administration." (PMID 32281248, 2020). "We therefore decided to further investigate SPP1 in our hyperglycemia model." (PMID 34046254, 2021). "STZ‐treated mice exhibit hyperglycaemia throughout their entire life without differences in fasting blood sugar (FBS) between WT and Spp1−/− mice at 4 and 6 weeks of age." (PMID 32281248, 2020).
nonalcoholic steatohepatitis (23 papers, 2010 to 2024). "It has been shown that macrophage-derived SPP1 has a protective effect against nonalcoholic steatohepatitis." (PMID 38731915, 2024). "SPP1 is also conjectured to function in the transformation of non-alcoholic steatohepatitis (NASH) to HCC like LPL." (PMID 36387855, 2022). "Given that SPP1 is predominantly secreted from macrophages, SPP1+ macrophages are widely recognized to regulate various diseases, such as cancers, cardiovascular diseases, tissue fibrosis, and nonalcoholic steatohepatitis." (PMID 38919629, 2024). "These macrophages express genes related to lipid metabolism (glycoprotein nmb (Gpnmb) and Spp1), which are also expressed in macrophages in mouse livers with non-alcoholic steatohepatitis (NASH) and obese adipose tissue, and are termed lipid-associated macrophages (LAMs)." (PMID 37082623, 2023). "To fully understand the role of OPN on the development of NAFL‐derived hepatocellular carcinoma (HCC), we applied a non‐alcoholic steatohepatitis (NASH)‐HCC mouse model on osteopontin‐deficient (Spp1−/−) mice analysing time points of NASH, fibrosis and HCC compared to wild‐type mice." (PMID 32281248, 2020).
Sepsis (22 papers, 2004 to 2025). Sepsis is defined as life-threatening organ dysfunction caused by a dysregulated host response to infection. "To evaluate SPP1, we measured the concentration of OPN in multiple CSF supernatants and blood plasmas acquired from sepsis-developed BM patients, and the results showed that CSF supernatants contained significantly higher OPN levels than blood plasmas." (PMID 36119025, 2022).
tuberculosis (22 papers, 2010 to 2025). A chronic, recurrent infection caused by the bacterium Mycobacterium tuberculosis. "Both TNC and SPP1 are matricellular proteins that are upregulated in active tuberculosis (TB) relative to healthy controls or latent TB; OPN (i.e., SPP1) and TNC may function as reliable biomarkers for monitoring TB activity." (PMID 31281837, 2019).
colitis (21 papers, 2011 to 2025). Inflammation of the colon. "After 7 days of induced colitis, the gene expression of Osm and Csf3 was at the same level in all experimental groups, while the gene expression of Spp1 was still higher in CβG− and CβGl+ groups compared to the HβG− group." (PMID 35163326, 2022). "A significant up-regulation of genes encoding the following cytokines and their receptors—Il13, Il16, Il27, Il2rb, Il2rg, Il6r Il10ra, Faslg, Ltb, Osm, Spp1, Tnf, Tnfsf14—was noted in animals with colitis (CβG−)." (PMID 31590413, 2019). "Interestingly, mice lacking SPP2 exhibited less DSS-induced weight loss, reduced colitis scores, and decreased proinflammatory cytokine secretion; however, mice lacking SPP1 demonstrated enhanced colitis severity." (PMID 38398179, 2024). "After 7 days of induced colitis, upregulation of the expression of 22 genes (Ccl2, Ccl3, Ccl4, Ccl5, Ccl6, Ccl7, Ccl12, Ccl17, Cxcl1, Cxcl2, Cxcl6, Cxcl9, Cxcl11, Ccr1, Ccr2, Ccr3, Ccr5, Ccr8, Cxcr2, Csf3, Osm, and Spp1) was observed in the CβG− group compared to the HβG- control group." (PMID 35163326, 2022).